ESPNL (espin like)
Description:
Binds to but does not cross-link actin. Required for the formation and maintenance of inner ear hair cell stereocilia and staircase formation. Essential for normal hearing.
Synonyms: FLJ42568
Tractability: PROTAC: ubiquitination databases record sites on it.
Gene: Protein-coding gene on chromosome 2 (238,100,340 to 238,133,287, forward strand). Ensembl gene ENSG00000144488.
Subcellular location: Cell projection, stereocilium
Subcellular location (Human Protein Atlas): Cytosol; Nuclear bodies; Nucleoplasm; Vesicles
Pathways (Reactome):
Sensory Perception: Sensory processing of sound by inner hair cells of the cochlea; Sensory processing of sound by outer hair cells of the cochlea
Gene Ontology:
Molecular function: protein binding; actin filament binding
Biological process: actin filament bundle assembly; sensory perception of sound
Cellular component: cytoplasm; stereocilium tip; stereocilium
Genetic constraint (gnomAD): Loss-of-function variants: 47 observed, 36.26 expected, observed/expected ratio (o/e) 1.3, 90% interval 1.02 to 1.65. The synonymous counts are far from expectation, so gnomAD's model fits this gene poorly and the ratio says little. Missense variants: 1,539 observed, 1,247.2 expected, observed/expected ratio (o/e) 1.23, 90% interval 1.18 to 1.29. Synonymous variants: 664 observed, 562.12 expected, observed/expected ratio (o/e) 1.18, 90% interval 1.11 to 1.26.
Homologues: Orthologues: chimpanzee ESPNL (99% identical), macaque ESPNL (95% identical), pig ESPNL (83% identical), dog ESPNL (80% identical), mouse Espnl (79% identical), rat Espnl (79% identical), rabbit ESPNL (72% identical), guinea pig ESPNL (65% identical), zebrafish espnlb (44% identical), zebrafish espnla (39% identical), Drosophila melanogaster f (18% identical), Caenorhabditis elegans ipla-3 (16% identical). Paralogues in human: ESPN (25% identical).
Diseases named in the same sentence as ESPNL in open-access papers:
ESPNL is named in the same sentence as 3 diseases in open-access papers, as found by Europe PMC text mining. Sharing a sentence is not in itself a finding about the gene and the disease. The quoted sentences say what the papers report.
Autoimmunity (1 paper, 2020). The occurrence of an immune reaction against the organism's own cells or tissues. "There is no prior evidence for the role of ESPNL in autoimmunity, but it is ubiquitously expressed." (PMID 32774345, 2020).
deafness (1 paper, 2025). An inherited or acquired condition characterized by the complete loss of the ability to hear from one or both ears. "Genes from the CAPZA family were involved with the regulation of the growth of actin filament and associated deafness (e.g., PLS1, LHFL5, OTOG, ESPN, and ESPNL)." (PMID 41465109, 2025).
tumor (1 paper, 2016). "An abridged list contains 23 hypermethylated genes and 4 hypomethylated genes (CACNA2D4;LRTM2, ESPNL, SECTM1, PCDH8) for AA tumor samples; whereas, 29 hypermethylated genes and 1 hypomethylated gene (BRSK2) are listed for the CA tumor samples." (PMID 27111221, 2016).